KCNJ15 (potassium inwardly rectifying channel subfamily J member 15)
Description:
Inward rectifier potassium channels are characterized by a greater tendency to allow potassium to flow into the cell rather than out of it. Their voltage dependence is regulated by the concentration of extracellular potassium; as external potassium is raised, the voltage range of the channel opening shifts to more positive voltages. The inward rectification is mainly due to the blockage of outward current by internal magnesium.
Synonyms: Kir4.2; Kir1.3; IRKK
Tractability: Small molecule: it belongs to a druggable protein family. Antibody: its Gene Ontology location is reachable by antibodies, with high confidence; UniProt places it where antibodies can reach, with medium confidence; UniProt predicts a signal peptide or a membrane-spanning region; the Human Protein Atlas places it where antibodies can reach. PROTAC: ubiquitination databases record sites on it.
Gene: Protein-coding gene on chromosome 21 (38,155,549 to 38,307,357, forward strand). Ensembl gene ENSG00000157551.
Subcellular location: Membrane; Cell membrane
Subcellular location (Human Protein Atlas): Plasma membrane; Cytosol; Vesicles
Pathways (Reactome):
Neuronal System: Activation of G protein gated Potassium channels; Inhibition of voltage gated Ca2+ channels via Gbeta/gamma subunits
Gene Ontology:
Molecular function: protein binding; inward rectifier potassium channel activity; potassium channel activity
Biological process: potassium ion import across plasma membrane; potassium ion transport
Cellular component: plasma membrane; membrane
Genetic constraint (gnomAD): Loss-of-function variants: 14 observed, 24.26 expected, observed/expected ratio (o/e) 0.58, 90% interval 0.38 to 0.9. The upper end of that interval is the gene's LOEUF score, 0.9, which puts it in group 3 of 6, group 1 being the genes least tolerant of losing a copy. Missense variants: 388 observed, 486.84 expected, observed/expected ratio (o/e) 0.8, 90% interval 0.73 to 0.87. Synonymous variants: 185 observed, 193.97 expected, observed/expected ratio (o/e) 0.95, 90% interval 0.85 to 1.08.
Homologues: Orthologues: chimpanzee KCNJ15 (100% identical), macaque KCNJ15 (99% identical), dog KCNJ15 (98% identical), mouse Kcnj15 (96% identical), rat Kcnj15 (96% identical), rabbit KCNJ15 (96% identical), guinea pig KCNJ15 (95% identical), pig KCNJ15 (95% identical), tropical clawed frog kcnj15 (73% identical), zebrafish KCNJ15 (54% identical), Drosophila melanogaster Irk1 (35% identical), Caenorhabditis elegans irk-1 (35% identical), and 4 more. Paralogues in human: KCNJ10 (60% identical), KCNJ1 (44% identical), KCNJ12 (37% identical), KCNJ18 (37% identical), KCNJ2 (37% identical), KCNJ4 (36% identical), KCNJ13 (36% identical), KCNJ14 (36% identical), KCNJ5 (35% identical), KCNJ3 (35% identical), KCNJ6 (34% identical), KCNJ11 (34% identical), and 3 more.
Diseases named in the same sentence as KCNJ15 in open-access papers:
KCNJ15 is named in the same sentence as 54 diseases in open-access papers, as found by Europe PMC text mining. Sharing a sentence is not in itself a finding about the gene and the disease. The quoted sentences say what the papers report.
type 2 diabetes (6 papers, 2014 to 2025). "KCNJ15 has also been identified as a susceptibility gene to type II diabetes mellitus though the focus to date has been on pancreatic β cells where Kir4.2 function is proposed to inhibit glucose-stimulated insulin secretion." (PMID 39348460, 2024). "KCNJ15, a member of the J subfamily of potassium inward rectifier channels, is mainly expressed in the human kidney and pancreas and is a risk gene for type 2 diabetes; its downregulation promotes insulin secretion." (PMID 36389709, 2022). "Regarding genetic factors, the KCNQ1 and KCNJ15 variants have been reported to affect the development of type 2 diabetes by impairing beta cell function." (PMID 25166121, 2014). "In addition, KCNJ15 gene mutation is related to type 2 diabetes, Alzheimer’s disease, epilepsy and other diseases." (PMID 40342929, 2025). "Additionally, KCNJ15 overexpression is associated with type 2 diabetes." (PMID 37623492, 2023). "In another study that identified a polymorphism involved in the onset and progression of type 2 diabetes, the KCNJ15 polymorphism was observed in many non-overweight diabetic patients of Japan, whose ability to secrete insulin tended to decrease over time." (PMID 26215867, 2015).
Alzheimer disease (4 papers, 2019 to 2025). A progressive, neurodegenerative disease characterized by loss of function and death of nerve cells in several areas of the brain leading to loss of cognitive function such as memory and language. "Genotype-phenotype analysis revealed that the variation at the KCNJ15-related SNP rs928771 locus affects the age of onset of Alzheimer’s Disease (AD), with a small number of allele carriers experiencing earlier onset." (PMID 40342929, 2025). "KCNJ15 has been shown to influence immune activity, with specific variants linked to an increased risk of Alzheimer’s disease in the Chinese population, possibly acting through immune modulation." (PMID 39684694, 2024). "These authors identified two common variants, GCH1 (rs72713460) and KCNJ15 (rs928771), showing nominal associations with Alzheimer's disease in Chinese patients." (PMID 31032141, 2019). "Additionally, KCNJ15 gene mutations are implicated in the progression of neurological diseases, such as Alzheimer’s disease and epilepsy." (PMID 40342929, 2025). "Interestingly, the KCNJ15 gene was also found to be significantly associated with Alzheimer's disease (AD) in a large‐scale genome‐wide association study of AD, where KCNJ15 was highly expressed in the immune system and involved in immune‐related events." (PMID 40566643, 2025).
renal carcinoma (4 papers, 2020 to 2025). A carcinoma arising from the epithelium of the renal parenchyma or the renal pelvis. "KCNJ15 downregulation promotes the progression of renal cancer by a process associated with epithelial-mesenchymal transition and metallothionein expression." (PMID 38358909, 2024). "Cancer research has revealed that KCNJ15, as a differentially expressed gene, correlates with the clinical prognosis of renal cancer, esophageal squamous cell carcinoma, breast cancer, and glioma." (PMID 40342929, 2025). "Currently, research on KCNJ15 and cancer primarily concentrates on renal cancer, esophageal squamous cell carcinoma, breast cancer, among others." (PMID 40342929, 2025). "Importantly, the overexpression of KCNJ15 was shown to significantly inhibit the proliferation, migration, and colony formation of renal cancer cells, arrest the cell cycle and induce cancer cell apoptosis, which may be a tumor suppressor gene in renal cancer." (PMID 36389709, 2022).
diabetes (3 papers, 2023 to 2025). "Given the role of acidosis and diabetes in renal fibrosis, it is possible that KCNJ15 is related to IF/TA progression according to its role in these areas." (PMID 37623492, 2023). "Moreover, diabetes is a risk factor in both PCOS and UCEC, and HMOX1, RTN1, and KCNJ15 are considered diabetes-related genes." (PMID 37363398, 2023).
glioma (3 papers, 2015 to 2025). A benign or malignant brain and spinal cord tumor that arises from glial cells (astrocytes, oligodendrocytes, ependymal cells). "In cancer research, KCNJ15 gene participates in the cancer process as a differential gene in a variety of cancers, such as kidney cancer, esophageal squamous cell carcinoma, breast cancer and glioma." (PMID 40342929, 2025).
renal cell carcinoma (3 papers, 2020 to 2025). "Studies reveal that KCNJ15 is significantly downregulated in renal cell carcinoma (RCC), and this reduced expression serves as an independent poor prognostic factor for clear cell RCC (ccRCC)." (PMID 40342929, 2025). "Bibliographic search evidenced that MAL, BANK1, CXCR2, and KCNJ15 genes play a tumor suppressive role in different types of cancer, including colorectal cancer, B-cell lymphoma, and renal cell carcinoma." (PMID 32825087, 2020). "Kir4.2(KCNJ15) is lowly expressed in renal cell carcinoma(RCC)." (PMID 36703789, 2022).
ankylosing spondylitis (2 papers, 2023 to 2024). An autoimmune chronic inflammatory disorder characterized by inflammation in the vertebral joints of the spine and sacroiliac joints. "KCNJ15, identified as a common marker for UC and ankylosing spondylitis, shows promise as a potential diagnostic marker." (PMID 38510241, 2024).
bladder cancer (2 papers, 2016 to 2022). "We constructed a prognostic model based on Necroptosis subtype-related prognosis DEGS by lasso algorithm and multivariate COX analysis, which consists of 6 predictors (CERCAM POLR1H, KCNJ15, GSDMB, EHBP1, TRIM38), among which CERCAM is closely related to bladder cancer." (PMID 35478725, 2022). "Notably, expression of several potassium channels is modified in bladder cancer vessels vs controls (KCNC4, KCNG4, KCNS2) and in angiosarcoma vs controls (namely KCNJ16, KCNQ2, KCNJ15, KCNJ12, KCNJ1)." (PMID 27716384, 2016).
depression (2 papers, 2013 to 2024). "RNA editing modifications were analyzed using a panel of eight genes (CAMK1D, GAB2, IFNAR1, KCNJ15, LYN, MDM2, PDE8A, PRKCB) that we previously identified and whose editing combinations were suggested as biomarkers to distinguish BD from unipolar depression and subcategories of BD patients." (PMID 39684694, 2024).
epilepsy (2 papers, 2025). A brain disorder characterized by episodes of abnormally increased neuronal discharge resulting in transient episodes of sensory or motor neurological dysfunction, or psychic dysfunction. "KCNJ15 was recently shown to be downregulated in patients with epilepsy and shown to be co-expressed with other genes associated with epilepsy in human brain tissue." (PMID 41339323, 2025). "Expression quantitative trait locus (eQTL) analysis showed that the epilepsy-related SNP rs2833098 may become a risk marker for epilepsy by regulating the expression level of KCNJ15 in human temporal lobe brain tissue." (PMID 40342929, 2025). "As a potential biological target for epilepsy, KCNJ15 requires further experimental verification and more evaluations in different populations." (PMID 40342929, 2025). "A comprehensive bioinformatics analysis revealed that KCNJ15 is significantly downregulated in the brain tissue of the medial temporal lobe in patients with drug-resistant epilepsy." (PMID 40342929, 2025). "Protein-protein interaction (PPI) analysis indicated that the protein encoded by KCNJ15 directly interacts with the two epilepsy drug targets encoded by GABBR1 and GABBR2, further supporting the role of KCNJ15 in epilepsy." (PMID 40342929, 2025).
esophageal squamous cell carcinoma (2 papers, 2020 to 2025). Esophageal squamous cell carcinoma (ESCC) is a type of esophageal carcinoma (EC) that can affect any part of the esophagus, but is usually located in the upper or middle third. "KCNJ15 is known to participate in insulin secretion, nervous system diseases, gastric acid secretion, kidney cancer, and esophageal squamous cell carcinoma." (PMID 33633772, 2020).
Insulin resistance (2 papers, 2015 to 2024). Increased resistance towards insulin, that is, diminished effectiveness of insulin in reducing blood glucose levels. "The genes adiponectin receptor 1, sestrin 3, KCNJ15 and G-protein coupled receptor 27 have all been described to play a role in insulin resistance, decreased insulin secretion and impaired blood glucose homeostasis." (PMID 25768297, 2015).
otosclerosis (2 papers, 2021 to 2024). Formation of spongy bone in the labyrinth capsule which can progress toward the stapes (stapedial fixation) or anteriorly toward the cochlea leading to conductive, sensorineural, or mixed hearing loss. "By analyzing the expression profile in otosclerosis patients, several studies have demonstrated the involvement of KCNJ15 in aberrant bone remodeling processes in humans." (PMID 38956513, 2024). "The expression of KCNJ15 increases in otosclerosis patients, which implies this gene is directly involved in abnormal bone remodeling in humans." (PMID 34706644, 2021).
proximal renal tubular acidosis (2 papers, 2023 to 2024). Proximal renal tubular acidosis (pRTA) is a tubular kidney disease characterized by impaired ability of the proximal tubule to reabsorb bicarbonate from the glomerular filtrate leading to hyperchloremic metabolic acidosis. "Notably, there is no aminoaciduria or glycosuria in either the Kcnj15 or Kcnj16 gene variants, suggesting that Kir4.2 or Kir5.1 dysfunction caused a phenomenon similar to the permanent forms of familial isolated proximal renal tubular acidosis." (PMID 36923292, 2023).
breast carcinoma (1 paper, 2025). "Evidently, KCNJ15 promotes the development of chemotherapy resistance in breast cancer by influencing lysosomal function." (PMID 40342929, 2025).
Hyperchloremia (1 paper, 2025). An abnormally increased chloride concentration in the blood. "In mouse kidneys, Kir4.2 and Kir5.1 are located on the basolateral membrane in the form of heterotetramers, and hyperchloremia acidosis, reduced threshold for bicarbonate reabsorption, and decreased urinary NH4+ can be observed in KCNJ15−/− mice." (PMID 40342929, 2025).
Hyperinsulinemia (1 paper, 2022). An increased concentration of insulin in the blood. "It seems that KCNJ15 works as a feedback control to protect against high insulin in the blood (hyperinsulinemia)." (PMID 35723340, 2022).
Sepsis (1 paper, 2025). Sepsis is defined as life-threatening organ dysfunction caused by a dysregulated host response to infection. "Notably, upregulation of ADCK1, IGF1R, and MAP3K1 at the transcriptional level was found to predict higher sepsis risk, while increased expression of BLK and KCNJ15 correlated with lower risk." (PMID 40761792, 2025).
tumor (9 papers, 2020 to 2025). "Additionally, KCNJ15, TSPYL5, RTN1, HMOX1, DCAF12L1, VNN2, and ANXA1 were found to be associated with survival time, tumor mutation burden (TMB), and immune infiltration in UCEC." (PMID 40342929, 2025). "Among them, FLRT3, ATP1A1, and KCNJ15 were expressed at decreased levels in tumor samples, and the expression of SAA1 was increased in tumor samples." (PMID 38358909, 2024). "The immunohistochemistry results suggested that the expression of TM4SF1, FASN, and IMPDH1 was significantly elevated in tumor tissue specimens, while the expression of KCNK5 and KCNJ15 was downregulated." (PMID 35480865, 2022). "In the TCGA-HNSC cohort, we observed the expression of 12 ion channel genes in tumor and normal tissues; ANO1, AQP9, BEST2, CHRNA5, and KCNJ15 were upregulated in HNSCC, while AQP1, AQP5, SCNN1G, and SCN4A were downregulated." (PMID 36389709, 2022). "The representative IHC images of normal/tumor and low/high grade tissues from HPA revealed that the degree of staining intensity of CD96, DDB1, IP6K2, PDCL3, TRIM38, and KCNJ15 were in correspondence with our predictions of coefficient." (PMID 34268106, 2021). "In the TCGA dataset, SLC25A37 was significantly upregulated in tumor tissues, while CPPED1 and KCNJ15 were significantly upregulated in adjacent non-tumor tissues." (PMID 38801430, 2024).
cancer (5 papers, 2020 to 2025). A tumor composed of atypical neoplastic, often pleomorphic cells that invade other tissues. "The findings also showed that the mRNA expression levels of TM4SF1, FASN, and IMPDH1 were higher in cancer tissues, whereas the mRNA expression of KCNJ15 was higher in normal tissues." (PMID 35480865, 2022). "KCNJ15 may contribute to cancer occurrence, migration, and drug resistance by engaging in the EMT process, regulating the cell cycle, and disrupting lysosomal function." (PMID 40342929, 2025). "KCNJ15 exhibits differential expression across various cancers." (PMID 40342929, 2025). "Evidently, KCNJ15 may play a role in cancer progression by regulating the cell cycle and inhibiting the EMT process, indicating that KCNJ15 could potentially serve as a target for cancer therapy." (PMID 40342929, 2025).
infection (4 papers, 2022 to 2025). The state of being infected such as from the introduction of a foreign agent such as serum, vaccine, antigenic substance or organism. "KCNJ15, an inward-rectifying potassium ion channel, plays a crucial role in bacterial clearance during infection." (PMID 40761792, 2025). "KCNJ15 was found to be involved in bacteria clearance in infection." (PMID 37077915, 2023). "To investigate the causal relationship between mycobacterial infection and KCNJ15 expression, we infected primary monocytes and THP-1 cells with Mtb and BCG (Bacillus Calmette–Guérin), respectively, and observed increased mRNA and protein expression upon infection." (PMID 35102304, 2022). "After infection with adenovirus carrying the KCNJ15 shRNA plasmid, the protein level of Kir4.2 decreases in primary rabbit gastric parietal cells, and these cells exhibit no response to histamine-induced acid secretion." (PMID 40342929, 2025).
KCNJ15 also shares sentences with these, for which no sentence is quoted: nervous system diseases (3 papers); breast adenocarcinoma (2); Hypokalemia (2); Obesity (2); Alkalosis (1); Aminoaciduria (1); angiosarcoma (1); Anxiety (1); atherosclerosis (1); atrial fibrillation (1); autism (1); B-cell lymphoma (1); channelopathies (1); colorectal cancer (1); diabetic retinopathy (1); Down syndrome (1); geographic atrophy (1); glioblastoma (1); gynecological cancers (1); head and neck cancer (1); ischemic stroke (1); kidney cancer (1); metabolic acidosis (1); neurodegenerative disease (1); oral carcinoma (1); osteosarcoma (1); Parkinson disease (1); polycystic ovary syndrome (1); renal fibrosis (1); retinal diseases (1).
A further 3 diseases each share a sentence with KCNJ15 in 1 paper.